SERPING1 (serpin family G member 1)
Diseases named in the same sentence as SERPING1 in open-access papers (continued):
Sharing a sentence is not in itself a finding about the gene and the disease.
cancer (16 papers, 1992 to 2025). A tumor composed of atypical neoplastic, often pleomorphic cells that invade other tissues. "Lastly, downregulated C1 Inhibitor (encoded by SERPING1) was shown to increase cancer risk." (PMID 36077244, 2022). "We conducted single‐cell analysis using cancer sample files from the TISCH database to identify the principal cell types that express SERPING1 and STEAP3 inside the TME." (PMID 39853609, 2025). "Based on our findings, we suggest that SERPING1 is emerging as a key component for modulating cancer metastasis in SR HCC cells." (PMID 39474998, 2025). "Therefore, we investigated which functions of SERPING1 are involved in cancer progression and resistance to sorafenib in HCC." (PMID 39474998, 2025). "In summary, sorafenib reduces HCC cancer progression might through the p‐ERK‐MMP‐2‐MMP‐9 cascade via upregulation of SERPING1." (PMID 39474998, 2025). "Collectively, our data highlight a novel regulatory mechanism of SERPING1, which might serve as a critical determinant of cancer progression and drug resistance in HCC." (PMID 39474998, 2025). "Upregulation of Serping1 (2.74-fold) and complement component 3a receptor 1 (C3ar1, 2.24-fold) demonstrated dynamic regulation of the complement system, which might be related to cancer cell apoptosis, nodule formation and MOF trafficking." (PMID 38887543, 2024). "The TIMER online analysis database was used to examine the expression of SERPING1 and STEAP3 in different types of cancer." (PMID 39853609, 2025). "In recent years, the roles of SERPING1 and IGFBP3 have garnered increasing attention as potential therapeutic targets for various diseases, including autoimmune disorders and cancers." (PMID 40377287, 2025). "Hence, the upregulated SERPING1 observed in our RNA-seq (while not validated in our combined cohorts) may also contribute to reduced cancer risk in children with ASD." (PMID 36077244, 2022). "Hence, our findings suggest a pivotal role for SERPING1 dysregulation in HCC, contributing to sorafenib resistance and cancer development." (PMID 39474998, 2025). "SERPING1, a protease inhibitor belonging to the serpin superfamily, can modulate extracellular matrix metalloproteinases (MMPs) activity, such as MMP‐2 and MMP‐9, to influence cancer cell motility." (PMID 39474998, 2025). "For example, targeting SERPING1 to modulate complement activation could be beneficial in treating autoimmune conditions, while IGFBP3 could be explored as a therapeutic agent in cancer and metabolic disorders due to its regulatory influence on cell growth and survival." (PMID 40377287, 2025).
cardiovascular disease (5 papers, 2020 to 2025). "To delve deeper, we investigated the causal relationship between genetically predicted SERPING1 overexpression and 17 cardiometabolic traits alongside 11 cardiovascular diseases." (PMID 39962118, 2025). "Limited evidence for longitudinal changes in levels of SERPING1 in human cardiovascular disease have previously been suggested as a link to low-grade levels of chronic inflammation." (PMID 32849183, 2020). "In summary, our findings suggest a reassuring safety profile when considering the application of SERPING1 overexpression for the future treatment of LC, with no substantial increase in cardiometabolic risks or susceptibility to cardiovascular diseases identified in our comprehensive assessment." (PMID 39962118, 2025).
immune dysfunction (3 papers, 2018 to 2025). "DEGs that enriched to “immune system diseases” played critical roles in cell-matrix communication (THY1, LVRN, LUM, TIMP3, SPOCK1, LGALS3BP, FAT2, and SERPINE2) as well as inflammation (IL1R2, CD22, PTGES, TNFSF10, IL2RB, C3, SERPING1, and IL-17RE)." (PMID 30131724, 2018).
kidney disease (3 papers, 2021 to 2024). "Expanding the sample size and including more types of kidney disease patients in future studies could help to further reveal the association between urinary SERPING1 and eGFR." (PMID 39835101, 2024).
SERPING1 also shares sentences with these, for which no sentence is quoted: acquired angioedema (56 papers); urticaria (18); Anxiety (10); lymphoproliferative disorders (10); Allergy (9); lymphoma (9); thrombosis (9); myocardial infarction (8); anaphylaxis (7); monoclonal gammopathies (7); viral infection (6); glomerulonephritis (5); multiple sclerosis (5); neurological disorders (5); endometriosis (4); glioblastoma (4); infectious disease (4); periodontitis (4); primary Sjögren syndrome (4); acute myocardial infarction (3); alexithymia (3); B cell lymphoma (3); blood disorder (3); Erythema (3); Hypertension (3); ischemic stroke (3); primary immunodeficiency (3); rheumatoid arthritis (3); venous thromboembolism (3); acute kidney injury (2).
A further 151 diseases each share a sentence with SERPING1 in 2 papers or fewer.